EPO (erythropoietin)
Diseases named in the same sentence as EPO in open-access papers (continued):
Sharing a sentence is not in itself a finding about the gene and the disease.
chronic kidney disease (continued). "However, the extensive damage to nephrotic structures caused by chronic kidney disease, especially within the cortex and medulla, hinders erythropoietin manufacturing and subsequent red blood cell production." (PMID 35156909, 2022). "However, patients in the EPO group were older than those in the non-EPO group (65 ± 13 vs. 57 ± 8 years) (mean ± SD) with more underlying diseases, including chronic kidney disease (CKD)." (PMID 34831360, 2021). "Insufficient EPO production in chronic kidney disease (CKD) can cause renal anemia." (PMID 33594180, 2021). "EPO-deficiency anemia occurs in chronic kidney disease (CKD) patients and in preterm neonates." (PMID 29535446, 2018). "However, in other studies, EPO had little benefit, and in patients with cancer or chronic kidney disease, thromboembolic complications, and/or mortality risks were associated with EPO treatment." (PMID 23675319, 2013). "Indeed, a single nucleotide polymorphism in the human EPO gene promoter is associated with increased EPO in the vitreous and severe microvascular complications in diabetes, proliferative diabetic retinopathy, and end-stage renal disease." (PMID 22567318, 2012). "Thus, the stage of chronic kidney disease was more severe in the former group, with a possibly more reduced residual EPO secretion, more important blood loss and more accumulation of anti-erythropoiesis inhibitors." (PMID 17216497, 2007). "Patients previously treated with r-HuEPO require higher darbepoetin doses than naive patients do, most likely due to a longer period of chronic renal failure, dialysis status, and reduced level of residual erythropoietin secretion, exacerbated iron loss and accumulation of erythropoiesis inhibitors." (PMID 17216497, 2007). "Intriguingly, we noted significantly decreased levels of circulating erythropoietin in Slc7a7 whole-body knockout mice, accompanied by reduced Epo gene expression and protein levels in the kidney, which are typically associated with kidney damage and chronic kidney disease." (PMID 39881295, 2025). "However, its value is influenced by various conditions like hemoglobinopathies, vitamin B12 deficiency, decreased erythropoiesis, administration of erythropoietin, iron, reticulocytosis, chronic liver disease, alcoholism, chronic renal failure, decreased erythrocyte pH, splenectomy, etc." (PMID 38694138, 2024). "Anemia is a frequent complication in patients with chronic kidney disease (CKD), as the cortical area of their kidneys is often deficient in the production of EPO." (PMID 39078527, 2024). "However, several studies have demonstrated that EPO deficiency was observed in patients suffering from chronic kidney diseases and could indicate the onset of kidney diseases in diabetic patients." (PMID 35656290, 2022). "In another anemic model, i.e., chronic kidney disease (CKD), the reduction in renal function caused erythropoietin deficiency, low blood iron and inflammation." (PMID 35396390, 2022). "While it was reported that elevated EPO levels are associated with poor survival in heart failure, diabetic chronic kidney disease (CKD), and kidney transplant recipients, its impact on renal outcomes remains to be determined." (PMID 31619722, 2019). "Recombinant human erythropoietin (rHuEPO) has revolutionized the treatment of anemia associated with chronic kidney disease (CKD)." (PMID 22111015, 2011). "This study investigated the relationships between hemoglobin, erythroferrone, hepcidin, erythropoietin, ferritin, transferrin saturation, and renal function markers across different stages of chronic kidney disease in comparison with healthy controls." (PMID 41227183, 2025). "Renal anemia is a common complication of chronic kidney disease (CKD), affecting up to 80% of dialysis patients, primarily due to erythropoietin (EPO) deficiency, with contributions from blood loss, iron imbalance, and inflammation." (PMID 41018998, 2025).
chronic kidney disease (continued). "In particular, in patients with chronic kidney disease (CKD), deficiencies of erythropoietin and iron may further reduce the lifespan of RBCs." (PMID 40643488, 2025). "Trunzo JA and colleagues analyzed 37 patients with chronic kidney disease, erythropoietin resistance, and secondary hyperparathyroidism who underwent parathyroidectomy." (PMID 40244253, 2025). "EPO resistance is a significant challenge in patients with chronic kidney disease or inflammatory diseases." (PMID 41012526, 2025). "Hepatocyte EPO production cannot compensate for the reduction in EPO production by the kidney in chronic kidney disease." (PMID 39996752, 2025). "Maintenance hemodialysis (MHD) is the main renal replacement therapy for patients with end-stage renal disease, and erythropoietin (EPO) is the main therapy for renal anemia in patients receiving maintenance hemodialysis." (PMID 41244199, 2025). "In a rat model of chronic renal failure, increased plasma cholesterol concentration was lowered by EPO treatment while LDL-R expression was unchanged." (PMID 39996752, 2025). "HIF-PH inhibitors such as Roxadustat and Vadadustat, used in the treatment of anemia related to chronic kidney disease (CKD) by enhancing HIF expression targeting the EPO gene under normoxia." (PMID 40343532, 2025). "Hypoxia-inducible factor-prolyl hydroxylase domain inhibitors (HIF-PHI) are to increase the production of EPO and haemoglobin in patients with chronic kidney disease." (PMID 41034642, 2025). "Erythropoietin resistance is present in some patients with chronic kidney disease, especially in those undergoing hemodialysis, and is often treated using roxadustat rather than iron supplements and erythropoiesis-stimulating agents (ESAs)." (PMID 39010898, 2024). "Erythropoiesis-stimulating agents (ESAs), such as erythropoietin, are used to treat anemia, especially in patients with chronic kidney disease (CKD) or those undergoing chemotherapy." (PMID 39728296, 2024). "With the decline of functional renal tissue in patients with chronic kidney disease, the body’s ability to produce sufficient erythropoietin in response to hypoxia in the kidney diminishes." (PMID 38172731, 2024). "On the one hand, patients with chronic kidney disease (CKD) may induce anemia due to reduced erythropoietin production, which causes a compensatory increase in cerebral blood flow." (PMID 37307828, 2024). "Recombinant human erythropoietin (rHuEPO) effectively treats renal anemia in chronic kidney disease (CKD) patients." (PMID 38528249, 2024). "The present study aimed to identify the effect of erythropoietin on the complement system in patients with chronic kidney disease." (PMID 39200211, 2024). "One key function of PHDi is to stimulate the expression of EPO that is altered in chronic kidney disease." (PMID 39078527, 2024). "The aim of the present study was to investigate the effect of erythropoietin administration, on the complement system, in chronic kidney disease patients." (PMID 39200211, 2024). "EPO and other erythropoiesis-stimulating agents (ESAs) have been widely used for three decades to correct severe anemia in patients with chronic kidney disease (CKD) or cancer." (PMID 39916952, 2024). "Chronic kidney disease, for example, can impair the kidneys' ability to produce erythropoietin, leading to decreased red blood cell production." (PMID 39634981, 2024). "HIF-prolyl hydroxylase (HIF-PH) inhibitors, which activate HIF-1, are used to treat chronic kidney disease by enhancing endogenous erythropoietin production." (PMID 38416732, 2024). "In patients with end stage renal disease, levels of erythrocyte asymmetric dimethylarginine, a naturally occurring inhibitor of NOS, was associated with low hemoglobin levels and erythropoietin resistance." (PMID 36895793, 2023). "Approximately 5–10% of patients with chronic kidney disease are resistant to EPO to a certain extent." (PMID 37791567, 2023).
chronic kidney disease (continued). "In patients with chronic renal failure, erythropoietin(EPO)-treated hemodialysis patients showed significantly increased amounts of TRPC5 mRNA in monocytes compared with EPO-free hemodialysis patients." (PMID 37404813, 2023). "In an animal chronic renal failure model, it was demonstrated that EPO exerts an inhibitory effect on hepcidin expression." (PMID 37374094, 2023). "It was previously believed that chronic lesions in the renal tubules and interstitium lead to insufficient EPO production in chronic renal failure." (PMID 36799117, 2023). "In fact, pilot studies performed in patients with chronic kidney disease and patients with autoimmune liver disease indicate that clinically employed doses of EPO reliably increase frequencies of peripheral blood Tregs." (PMID 35389892, 2022). "For example, Roxadustat, which leads to increased endogenous erythropoietin generation, improved absorption of iron and anemia amelioration in chronic kidney disease (CKD)." (PMID 35205167, 2022). "In context of disease, EPO has been used for therapy for highly vascularized tissues, such as the kidney in chronic kidney disease (CKD)." (PMID 35769460, 2022). "In individuals with chronic renal failure, erythropoietin given subcutaneously to treat chronic anemia raises BP by 10 mmHg." (PMID 36000139, 2022). "The main treatment for renal anemia in end-stage renal disease (ESRD) patients on hemodialysis is erythropoiesis (EPO)." (PMID 35937691, 2022). "Compared to mesenchymal stem-cell MVs (untreated), the EPO-treated mesenchymal stem-cell MVs had a greater benefit in reduction of apoptosis appearance in mice kidneys with unilateral ureteral obstruction, a chronic kidney disease model." (PMID 36139786, 2022). "In patients with chronic renal failure, the level of erythropoietin (an erythropoietic hormone) is low, leading to decreased red blood cell count." (PMID 35139138, 2022). "Even though anemia in chronic kidney disease (CKD) results mainly from the decreased production of erythropoietin, eryptosis seems to be a contributing factor." (PMID 36498741, 2022). "Renal anemia is a common complication in chronic kidney disease (CKD), associated with decreased production of erythropoietin (EPO) due to loss of kidney function, and subsequent decreased red blood cell (RBC) production." (PMID 35813388, 2022). "Recombinant human erythropoietin (rHuEPO) is a drug given to patients who have low hemoglobin related to chronic kidney disease or other anemia-related diseases." (PMID 37675011, 2022). "In chronic kidney disease, EPO production is usually in a disruption state, leading to a decrease in Hb (Hb < 13 g/dl for men and <12 g/dl for women), labeled as renal anemia." (PMID 35281917, 2022). "ESAs therapy represented by recombinant human erythropoietin (rHuEPO), is the major treatment for anemia in patients with chronic kidney disease (CKD) or patients receiving chemotherapy (Drüeke and Massy, 2019)." (PMID 35517793, 2022). "Anti-EPO antibodies were mostly found in patients with chronic kidney disease who received recombinant human erythropoietin (rHuEPO) injections subcutaneously." (PMID 36524109, 2022). "Noshad conducted a study in which a rise in blood pressure was detected in end-stage renal disease patients who received erythropoietin therapy." (PMID 33628672, 2021). "Hemodialyzed end-stage renal disease patients also demonstrated EPO-stimulated miRNA-210 as a result of JAK2/STAT5 signal transduction in peripheral blood mononuclear cells." (PMID 34281163, 2021). "We sought to investigate the effects of resistance training (RT) combined with erythropoietin (EPO) and iron sulfate on the hemoglobin, hepcidin, ferritin, iron status, and inflammatory profile in older individuals with end-stage renal disease (ESRD)." (PMID 34579127, 2021).
chronic kidney disease (continued). "The HIF pathway has been implicated in the regulation of hematopoiesis and roxadustat has been shown to increase hemoglobin and EPO levels as well as reductions in hepcidin in patients with chronic kidney disease in phase III trials." (PMID 33807279, 2021). "Recombinant human EPO has played a part in the treatment of renal anemia in patients with end-stage renal disease (ESRD) or chronic kidney disease." (PMID 33928100, 2021). "In turn, the secretion of erythropoietin is disturbed in chronic kidney disease, where the production of this hormone is gradually reduced." (PMID 32560029, 2020). "Typically, patients with advanced chronic kidney disease will receive EPO at 50-100 IU/Kg three times a week, and patients with hematological malignancies (MDS, MM) will start with higher doses, i.e., 150 IU/Kg three times a week or 40,000 IU once a week." (PMID 32471308, 2020). "Human recombinant erythropoietin (rHuEPO) is often used in the treatment of diseases associated with a decreased production of red blood cells (RBC), such as chronic renal failure." (PMID 32748255, 2020). "This randomized, active-controlled study aimed to compare the efficacy and safety of DA-α and EPO for the treatment of renal anemia among Indian patients with ESRD (end-stage renal disease) undergoing dialysis." (PMID 30866856, 2019). "The objective of this study was to compare the efficacy and safety of DA-α injection versus EPO for treating renal anemia amongst Indian patients with end-stage renal disease (ESRD) undergoing dialysis." (PMID 30866856, 2019). "Emerging data from the chronic kidney disease (CKD) field suggest that both iron deficiency and EPO lead to an up-regulated expression and concomitant cleavage of a phosphate-regulating hormone, fibroblast growth factor 23 (FGF23), another risk factor for mortality." (PMID 31170159, 2019). "One of the more alarming instances of immunogenicity leading to life-threatening safety concerns is pure red cell aplasia (PRCA) in chronic renal failure patients treated with recombinant human erythropoietin (EPO)." (PMID 29325166, 2018). "In patients with advanced-stage chronic kidney disease, treatment of chronic anemia requires routine injections of recombinant erythropoietin (EPO)." (PMID 30406106, 2018). "Epoetin (recombinant human EPO) has been approved for the treatment of anemia in patients with chronic kidney disease or those receiving chemotherapy for more than two decades." (PMID 29385149, 2018). "The introduction of EPO therapy markedly decreased the necessity of transfusion in patients with end-stage renal disease." (PMID 29047386, 2017). "Essential medicines involved in the management of chronic kidney disease were ferrous salt, iron sucrose, erythropoietin, vitamin D3 + calcium carbonate and calcitriol." (PMID 28056960, 2017). "In animal studies, erythropoietin gene and protein expression were markedly inhibited in rats with chronic kidney disease; however, this effect was significantly reversed by lowering serum indoxyl sulfate with AST-120." (PMID 29137321, 2017). "The vast majority of cases of patients developing AAbs to erythropoietin (EPO) are correlated with long-term usage of erythropoiesis-stimulating agents (ESAs) in patients with chronic kidney disease (CKD)." (PMID 31557985, 2016). "The list also includes erythropoietin given to patients with chronic renal failure or oncological ailments, Humira®, Remicade® and Enbrel® in rheumatoid arthritis, psoriasis, and other immunological diseases." (PMID 28090427, 2016). "An early study on patients with chronic renal failure treated with EPO reported an increase in type I muscle fiber diameter and in muscle glycogen content when compared to baseline levels." (PMID 27458387, 2016). "Patients with end-stage renal disease on hemodialysis treated with recombinant EPO have been shown to have improvement in insulin sensitivity." (PMID 27119016, 2016).
chronic kidney disease (continued). "Several previous studies showed that plasma LPS (i.e. bacterial cell wall fragment) level is related to systemic inflammation, erythropoietin resistance, and cardiovascular disease in chronic kidney disease." (PMID 26010741, 2015). "On the contrary, clinical observations demonstrate that the mortality and morbidity rate are elevated in patients with acute ischemia stroke or chronic kidney diseases when administrated with EPO." (PMID 26101463, 2015). "EPO is not free from side effects, mainly cardiovascular events reported in patients affected by heart or chronic kidney diseases, undergoing prolonged EPO administration." (PMID 26636649, 2015). "Patients included in the model were those with chronic kidney disease stages 3 to 5, who have renal anemia and require treatment with erythropoietin stimulating agents." (PMID 25780617, 2014). "Resistance to erythropoietin (EPO) affects a significant number of anaemic patients with end-stage renal disease." (PMID 24920275, 2014). "Chronic kidney disease (CKD) blunts erythropoietin production, a proanemic effect that is compounded by other factors such as accelerated erythrocyte destruction and widespread use of concomitant medication such as ACE inhibitors and ARBs." (PMID 24883202, 2014). "Previous studies and clinical evidence have demonstrated that EPO and its derivatives are important in renal protection during chronic kidney disease." (PMID 24926362, 2014). "In a rat model of chronic renal disease progression, EPO treatment reportedly activated AKT and eNOS, and reduced progressive vascular injury and organ failure." (PMID 24918289, 2014). "Even in chronic kidney disease, treatment with recombinant human erythropoietin decreases urinary levels of protein and of biomarkers of renal injury, as well as reducing levels of markers of oxidative stress." (PMID 22235348, 2012). "Glucose and lipid metabolism were studied in seven patients with end-stage renal disease being treated with erythropoietin to correct anemia." (PMID 21754921, 2011). "A recent study demonstrated that the T/T genotype of the rs1617640 SNP, located in the promoter region of the erythropoietin (EPO) gene, is significantly associated with diabetic retinopathy and end-stage renal disease in patients with diabetes." (PMID 21078205, 2010). "Erythropoietin (EPO) was introduced for clinical use in 1989 in the treatment of end-stage renal disease (ESRD)." (PMID 19521513, 2009). "Intervention with erythropoietin has been shown to improve the quality of life for anaemic patients in chronic renal failure." (PMID 18752687, 2008). "Upon introduction of recombinant human EPO into the clinic, cognitive improvement of patients with chronic renal failure was noted during EPO treatment, but attributed to its hematopoietic effects." (PMID 18782446, 2008). "The introduction of erythropoietin-stimulating agents (ESAs) in the 1980s represented a major therapeutic advance for renal anemia, significantly enhancing the quality of life in end-stage renal disease (ESRD) patients while reducing dependence on blood transfusions." (PMID 41383483, 2025). "One area of investigation could be its effect on chronic kidney disease patients with erythropoietin resistance." (PMID 40244253, 2025). "Initial studies showed that in anemic patients with chronic kidney disease on dialysis, EPO treatment was administered three times weekly after dialysis dose dependently increased hematocrit, up to 10 percent at 3 weeks, and reduced the transfusion requirement." (PMID 38628440, 2024). "Thus, in chronic kidney disease, when EPO production is restricted due to kidney damage, Hb levels are higher for higher BMI and lower EPO doses are required to maintain Hb levels in obese compared to normal weight patients." (PMID 39348390, 2024).